IL6 (interleukin 6)
Diseases named in the same sentence as IL6 in open-access papers (continued):
Sharing a sentence is not in itself a finding about the gene and the disease.
infection (continued). "Our systems biology analysis revealed that 13 hub genes, including the classical inflammatory genes (IL6, NFKB2, JUN, IL-1β, and CXCL2) which regulate retinal innate responses during infection." (PMID 26865111, 2016). "Following trauma or infection reactive astrocytes can produce a number of cytokines (e.g., CXCL10, CCL2, and IL-6) that mediate innate immune function such as recruitment of monocytes and microglia." (PMID 27143977, 2016). "By studying the function of this microRNA in mice, they found that it controlled neutrophil recruitment to the lung during infection by regulating the expression of key neutrophil chemoattractants, including CXCL2 and CCL3, as well as interleukin-6 (IL-6)." (PMID 27048801, 2016). "In sum, these results indicate that the expression levels of proinflammatory cytokines and chemokines IL-1beta, IL-6, IL-8 and LITAF in CEFs and DEFs showed different patterns following infection with NDVs of different pathogenicities." (PMID 26975566, 2016). "The secretion of inflammatory cytokines TNF-α, IL-1β, IL-6 and IFN-γ were induced in human PBMC from 1 day after infection." (PMID 27489303, 2016). "Seven days post infection, CS + IAV mice had increased mRNA expression of pro-inflammatory chemokines (CCL-2, CXCL-2), cytokines (GM-CSF, TNF-α, IL-1β, IL-6) and proteases (MMP-12) compared to sham + IAV + diluent mice." (PMID 26877172, 2016). "Significantly higher levels of the proinflammatory cytokines IL-6 and IL-8 were also observed after ANDV-infection, at day 25 p.i. for IL-6 and at days 20–25 p.i. for IL-8." (PMID 26907493, 2016). "It is suggested that the ensemble of CD8-positive signals in tissues was associated with the increased level of proinflammatory cytokines (IL1β and IL6) during both GPV and TMUV infection." (PMID 27150912, 2016). "BAL fluid levels of IFN-α, IFN-γ, TNF-α, IL-6, MCP-1 and MIP-2 increased following infection, with levels of IFN-γ and MCP-1 being significantly higher in Ctsl-/- mice than in Ctsl+/+ mice (at days 7 and 14, respectively)." (PMID 27716790, 2016). "Six hours after infection, gene changes involved pathways such as HMGB-1, interleukin (IL)-2, IL-6, IL-8, janus kinase/signal tranducer and activator of transcription (JAK/STAT), interferon, and ERK 5 signaling (P < 0.01)." (PMID 27119120, 2016). "IL-6 is a pro-inflammatory cytokine secreted by T cells and macrophages during infection and after tissue damage; CRP is an acute-phase protein that increases after IL-6 section." (PMID 26275545, 2016). "There was a significant increase at day 7 relative to day 5 post-infection in abundance of interleukins (IL) including IL1B, IL2, IL4, IL5, IL6, IL10 and IL13." (PMID 27311020, 2016). "Besides chemokines, cytokines such as TNF-α are released acutely in response to injury or infection, and function to initiate and maintain the inflammatory process in part by stimulating other pro-inflammatory cytokines (e.g., IL-1α, IL-1β, and IL-6) and chemokines (e.g., CCL2, CCL3, and CXCL2)." (PMID 26860080, 2016). "Lung IL-6 and TNFα responses were similar in all the mouse strains compared to to those of wildtype mice following Ft LVS infection or SchuS4 infection." (PMID 27926940, 2016). "From an immunological perspective, Lao/14 infection induced the expression of the pro-inflammatory cytokines IFN-γ and IL-6 to an extent similar to that observed in chickens infected with HPAI H5N1 viruses." (PMID 27631618, 2016). "Our results show up-regulated expression of cytokines including TNF-α, IL-6 and IL-10 in 2%DMSO-treated DENV-infected mice and SB203580 treatment significantly reduced the TNF-α, IL-6 and IL-10 expression upon DENV-infection." (PMID 26901653, 2016). "Three days post infection, CS + IAV mice had increased mRNA expression of pro-inflammatory chemokines (CCL-2, CXCL-2), cytokines (GM-CSF, TNF-α, IL-1β, IL-6) and proteases (MMP-12) compared to sham + IAV + diluent mice." (PMID 26877172, 2016).
infection (continued). "IL-6 and MCP-1 levels in the wild type mice were consistently higher than in CypA+ mice throughout the infection." (PMID 27354005, 2016). "The anti-TNF-α Ab suppressed IL-6, MCP-1, and IFN-γ levels, suggesting that the severe response to infection was triggered by TNF-α." (PMID 26844767, 2016). "Infection of epithelial cells by IFV increases the expression of TNF-α, IL-6, IL-8, CCL2 (MIP-1), CCL5 (RANTES), CCL3 (MIP-1α), and CXCL10 (IP-10)." (PMID 28066442, 2016). "West and colleagues suggested that murine pulmonary infection induced by inhalation of B. pseudomallei leads to increases in IFN-γ, IL-10, IL-1β, IL-6, KC and TNF-α in the lung 1 day after infection." (PMID 27529172, 2016). "There were significant differences in the levels of IFN-α, IFN-γ, IL-6, IL-7, IL-8, IL-10, IL-12p70, IP-10, MCP-1, sCD40L and VEGF in patients with DI, DW or SD infections." (PMID 26982706, 2016). "In the early stage of infection, STAT3 also strongly represses the production of inflammatory cytokines such as IL-6, while enhancing secretion of anti-inflammatory IL-10." (PMID 27384401, 2016). "In the HNE cells obtained from both groups of subjects, pretreatment with L‐carbocisteine (72 h) reduced the baseline secretion of IL‐6 and IL‐8 prior to RV14 infection." (PMID 27957326, 2016). "The greatest effect of ERK inhibition was observed in spleen samples, where there was a significant decrease in the secreted levels of IFN-γ, MCP-1, IL-6, and TNF-α in mice treated with PD0325901 prior to infection (at day −1) compared to PBS-treated controls." (PMID 27714591, 2016). "In this research, though the magnitude and duration of each cytokine differed between the two Listeria, the trends along with infection are same, which are increase of TNF-α, IL-6, IL-12, and IFN-γ and decrease of IL-4." (PMID 27375558, 2016). "The results demonstrate that the level of mRNA expression of IL-6, IL-8, IL-10, COX-2, IL-1β, IL-18, and TNF-α were significantly upregulated in peripheral blood monocytes following infection with H. parasuis for 3 or 6 h (p < 0.01)." (PMID 27502767, 2016). "After infection with A/WSN/33(H1N1), IL-6 and MCP-1 levels began to rise at 3 d.p.i. and peaked around 7 d.p.i. before dropping at 9 d.p.i. in both the CypA+ and wild type mice." (PMID 27354005, 2016). "Towards the terminal stage of infection, on day 6, transcript levels of some cytokines in HA-MARV-infected animals began to significantly increase, notably IL-6 and IL-4." (PMID 27976688, 2016). "H5N1 induced significantly higher levels of TNF-α, IL-6, IL-8, IL-10 and MCP-1 than those of H7N9 viruses at 48 h post-infection." (PMID 26975414, 2016). "TLR7/9-/- mice produce increased levels of IL6, TNF-α, and IL17A during Histoplasma infection, and similar results have been observed for the endemic fungal pathogen P. brasiliensis during infection of TLR9-/- mice." (PMID 27459510, 2016). "Immunoblotting showed that after PAO1 infection, the levels of both total and phosphorylated STAT3 were increased in Lyn-silenced MH-S cells, indicating that Lyn regulates the IL-6/STAT3 signaling pathway." (PMID 29263906, 2016). "Suppression of IL-1β, IFN-γ as well as IL-6 by the Riboflavin and CIP or AZM treated macrophages at late stage of infection further confirms their anti-inflammatory nature." (PMID 27932936, 2016). "Our findings suggest that IL-6 and KC/GRO cytokines can be a potential disease severity biomarker and/or marker for the progression/remission of infection." (PMID 27110056, 2016). "Intracellular infection with the S. aureus WCH-SK2WT elicited a more consistent innate immune response in comparison to intracellular S. aureus WCH-SK2SCV infection with an increased expression of IL1B, IL6, IL12, MMP9, and TLR2 at 24 h." (PMID 28083514, 2016). "Fifty hours after infection, 92.3% of the WT animals were still alive, while all TNFR1−/− and TNFR1-IL-6−/− mice were dead and 28.6% of the IL-6−/− mice were still alive." (PMID 27057100, 2016).
infection (continued). "Serum levels of IL-6 and IL-17 were elevated following RSV infection, and were higher following RSV reinfection than primary infection." (PMID 27747195, 2016). "Among the well-known Th2 cytokines, the expression of IL6, IL10 and IL13 was upregulated by infection in both breeds." (PMID 27197554, 2016). "The major role NF-κB plays in modulating inflammation in response to injury and infection in multiple tissues was of interest to us in the CXCR2−/− mice exposed to CS, particularly since we observed differential regulation in KC and IL-6." (PMID 27826243, 2016). "After infection for 24 h, different concentrations of recombinant TNF-α or IL-6 were added to the PCV2-infected PK-15 cells, which were further cultivated for 12 h." (PMID 27581515, 2016). "<0.01 or P<0.05) between the three infection groups and the control group with the exception of the IFN-γ and IL-6 levels in the spleen between the Sp-only and PBS group and the TNF-α levels of the lung between the CIV-only or CIV/Sp group and the PBS group." (PMID 27259293, 2016). "At 36 h post-infection, the qPCRs showed that TNF-α induced IL-6 expression, and higher IL-6 and TNF-α levels were induced by PCV2 when SOCS3 was silenced, compared with control cells." (PMID 27581515, 2016). "Seven days post infection, CS + IAV mice had increased mRNA expression of pro-inflammatory chemokines (CCL-2, CXCL-2, CXCL-9, CXCL-10), cytokines (GM-CSF, TNF-α, IL-1β, IL-6) and proteases (MMP-12) compared to sham + IAV + diluent mice or CS + diluent mice." (PMID 26877172, 2016). "ARDS patients with overexpressed IL-6, CXCL16, or IGFBP-4 had significantly longer hospital stay and higher incidence of secondary infection." (PMID 27095254, 2016). "To further confirm the link between decreased TWEAK concentrations and septic disease we performed correlation analysis revealing that TWEAK concentrations closely correlated to markers of infection in these patients (CRP, PCT and IL-6)." (PMID 27124414, 2016). "At the early stages of infection, TNF-α, IL-1β, IL-6, and IL-8 pro-inflammatory cytokines are produced and stimulate immune cells leading to activation of an inflammatory cascade." (PMID 28066425, 2016). "In contrast to the release of pro-inflammatory cytokines TNFα, IL-1β and IL-6, the release of FKN increased from 24 h up to 72 h post infection." (PMID 26739172, 2016). "Three days post infection, sham + IAV + vehicle mice had increased mRNA expression of pro-inflammatory chemokines (CCL-2, CXCL-2, CXCL-10), cytokines (GM-CSF, TNF-α, IL-1β, IL-6) and proteases (MMP-12) compared to sham + diluent + vehicle mice." (PMID 26877172, 2016). "Critically, on day 4 post-infection, IL-1β, TNFα, IL-6, CCL2 and CCL5 concentrations were significantly reduced in BAL fluid while IL-6 and IL-18 were reduced in the sera." (PMID 27283237, 2016). "The expression of TLR3, TLR7, IL-6, IFN-alpha, IFN-gamma, MHC-I and MHC-II, except for IL-8, were also greater in CEFs than in DEFs in response to infection to both viruses or treatment with poly(I:C)." (PMID 26975566, 2016). "In ileum inflammatory genes were overexpressed (e.g., IL-1B, IL-6, IL-8, IL1RAP, TNFα), indicating a strong immune response at all times of infection." (PMID 26738723, 2016). "Infection of H9N2 on HPMECs induced a high level of chemokines and cytokines production including IP-10, RANTES, IL-6, IFN-β and IFN-γ1." (PMID 26732368, 2016). "H56 in combination with CAF01, IC31® and GLA-SE all primed IFN-γ, IL-6 and TNF-α responses prior to infection and all of these cytokine responses remained two weeks after challenge." (PMID 26791076, 2016). "In this study, total spleen cells were shown to secrete TNF-α, IFN-γ, IL-6, IL-10, CCL3, and CXCL9, suggesting an activation of splenic cells during the infection and a polarization towards a Th1 response." (PMID 27905502, 2016).
infection (continued). "Consistent with the data of expression of inflammatory genes in our in vitro experiment, infection with LV-VNN1 increased the plasma concentrations of TNF-α, IL-1β, and IL-6 by 32.8%, 31.8%, and 56.5%, respectively." (PMID 27281478, 2016). "We observed the levels of expression of previously reported cytokines such as IL6, and CXCL8 (IL8) increase between 4 and 7 days post-infection." (PMID 27595844, 2016). "In contrast, 6 h after infection, markedly higher serum levels of CXCL1, TNFα, and IL-6 were detected in mice infected with biofilm-released cells than in the biofilm cell-infected counterparts." (PMID 27729907, 2016). "Our study confirms the usefulness of determining urinary IL-6 to differentiate between APN and LUTI in children and also indicates that the process of recovery from the infection results in normalization of urinary IL-6 levels." (PMID 27564295, 2016). "Intracellular WCH-SK2WT infection induced mRNA expression of TLR2, pro-inflammatory cytokines (IL1B, IL6, and IL12) and tissue remodeling factors (MMP9)." (PMID 28083514, 2016). "Upon infection with VSV and HSV-1, the production of IL-6 and IFNβ was significantly impaired in macrophages after Fbxo21 knockdown." (PMID 27063938, 2016). "We show that IL-17-mediated inflammation correlated with production of inflammatory cytokines (such as IL-6, IL-1β and TNF-α) that were profoundly increased at the early times upon infection including CLP treatment." (PMID 27389701, 2016). "The transcriptional levels of IL-6, TNF-a, IL-1β and MCP-1 were remarkably increased in the early stage of infection (within 12 h) and gradually decreased to their basal levels by 24 hpi." (PMID 27995095, 2016). "IL-6, TNF-a, and MCP-1 levels induced by WT strain were obviously higher than ΔVirD4 strain infection at 12 hpi." (PMID 27995095, 2016). "Second, higher TGF-β production early in infection will further inhibit CFTR-mediated Cl− secretion by HET respiratory epithelial cells and also induces IL-6 production by HET AMs." (PMID 25840995, 2015). "Macrophage activation up-regulated TNF-α and IL-6 and down-regulated IL-10 production upon PAO1-L infection and differences between the effects of IFN-γ and GM-CSF were observed." (PMID 25706389, 2015). "We therefore considered it of interest to examine the impact of MyD88 deficiency on the concentrations of proinflammatory cytokines (TNF-α, IL-1β, IL-6) and CXC chemokines (KC, MIP-2) after infection with D39 or D39Δcps." (PMID 25700108, 2015). "The infection was characterized by a significant up-regulation of TNF-α gene expression, while expressions of IFN-α2, IFN-β1, IFN-γ and IL-6 remained unchanged compared to mock-infected controls." (PMID 26274828, 2015). "Levels of IL-6 and TNF-α peaked at 48 hours post-infection, while they were significantly decreased by day 4 post-challenge." (PMID 26114641, 2015). "Infection of WT mice by a virulent strain of C. albicans typically results in a 100-fold induction of TNF-α mRNA and several thousand fold induction of IL-6 mRNA." (PMID 26010544, 2015). "This study also confirmed that there is a time lag of 6 to 8 hours until APR becomes positive after infection onset as APR is a protein produced in the liver in response to stimulation with IL-1β and IL-6." (PMID 25667565, 2015). "The cytokines, IL1, IL18, IL6, IL12, and IL17, can interact with T cells to resist infection in humans and mice." (PMID 26369556, 2015). "Higher levels of inflammatory cytokines, including IL-6, IFN-γ, TNF-α and MCP-1, were released in the livers of BG-exposed and unexposed malnourished mice 3 days post-infection compared with control, infected mice." (PMID 26241678, 2015). "A prior study supported our findings, in that infection of A549 by four RSV clinical isolates resulted in the differential concentration of cytokine/chemokine induced, including that of IL-6, IL-8 and RANTES." (PMID 26473163, 2015).
infection (continued). "In this study, primers for quantitative real time PCR for Saimiri IFNγ, TNFα, IL2, IL6, IL10, and IL12 were validated and used in a study of splenic responses in S. sciureus during blood infection by P. falciparum." (PMID 25890318, 2015). "The replacement of hepatic cells lost to infection, trauma, and inflammation is primarily mediated through IL-1 family cytokines, TNF-α, and IL-6 (all transcriptional targets of NF-κB) through their induction of the inflammatory acute phase response." (PMID 26635450, 2015). "Levels of IL-1ß, IL-6, and TNF-α increased by 72 hours post-infection in drug treated animals, a time point at which bacterial burdens were just beginning to become significantly different than those of controls." (PMID 26381144, 2015). "One hour after infection with ΔbgsA, plasma concentrations of TNF-α, IL-6, and MIP-2 were significantly increased in mice infected with ΔbgsA as compared to mice infected with wild-type bacteria or ΔbgsB." (PMID 26172831, 2015). "PAM at 6 h infection expressed TNF-α and IL-6 (pro-inflammatory cytokines) more highly with the two avian than the three mammalian influenza viruses." (PMID 26642934, 2015). "The results showed significant reductions in TNF-α, IL-1, IL-6, MCP-1, RANTES, and IFN-α in the MJWQH treated mice on day 4 after infection." (PMID 26089947, 2015). "GM-CSF treatment also increased the postoperative leukocyte counts while other markers of inflammation and infection such as temperature, CRP, PCT and IL-6 remained unaffected." (PMID 26641243, 2015). "We observed a significant decline in the levels of proinflammatory cytokines MIP-2 at ZT0 and ZT12 and IL-6 at ZT12 in the Air+Virus and CS+Virus groups 9 days post-infection compared to uninfected CS-exposed mice." (PMID 25923474, 2015). "Infection of adherent monocytes with EBOV in vitro resulted in secretion of IL-1β and IL-6, along with the chemokines IL-8 and RANTES." (PMID 26512687, 2015). "We observed a significant down-regulation of TNF-α, IL-1β, IL-6 and IFN-γ, compared with the infection control, by ELISA and qPCR." (PMID 26405764, 2015). "At 48 hours post infection (HPI), R. conorii (ISF) induced a significant elevation of IL-8 and IL-6 while R. massiliae induced a statistically significant elevated amount of MCP-1 at both transcriptional and protein synthesis levels." (PMID 26394396, 2015). "Serum levels of the pro-inflammatory cytokines IL-1ß, IL-6, IL-12, and TNF-α and the anti-inflammatory IL-10 appeared similar in anesthetized and Intralipid control animals during the first 48 hours post-infection." (PMID 26381144, 2015). "The local innate immune response of mammary glands was swiftly activated after S. aureus inoculation during the initial stage of infection, characterized by up-regulation of gene expression of TLR2, NOD2, TNF-α, IL-1β, IL-6, and CXCL1." (PMID 25990971, 2015). "According to previous studies, an appropriate amounts of cytokines, such as IL-1β, IL-6 and TNF-α, is beneficial in response to infection, but overstimulation of the immune system can have detrimental effects." (PMID 26635958, 2015). "RV14 infection increased the secretion of IL-6 into the supernatants of the untreated HTE and HNE cells and the cells pretreated with vehicle at 72 h after infection." (PMID 26462747, 2015). "We also proved that expression of three inflammatory cytokines, IL6, IL-8 and TNF-α in A549 cells augmented clearly during infection by A. fumigatus." (PMID 26273834, 2015). "In contrast, another study produced contradictory results to ours, with higher levels of IL-8, IL-6, and ICAM-1 expression in CTRL cells (CFT1-LCFSN) compared to CF cells (CFT1-ΔF508) after infection." (PMID 26485688, 2015). "Splenocytes of P. falciparum-infected monkeys stimulated with P. falciparum-pRBCs showed increased expression levels of IFNγ, IL6 and IL12 on d7 of infection." (PMID 25890318, 2015).